E2F3 (E2F transcription factor 3)
Diseases named in the same sentence as E2F3 in open-access papers (continued):
Sharing a sentence is not in itself a finding about the gene and the disease.
bladder cancer (continued). "Likewise, a RBP-induced structural switch modulating miRNA-mediated gene expression by PUM proteins has also been described on mRNAs coding for oncogene E2F transcription factor 3 (E2F3), which is strongly repressed by the cooperative action of miR-506 and PUM1 in bladder carcinoma cells." (PMID 26404389, 2015). "We also found that QKI‐6 could post‐transcriptionally down‐regulate E2F3 expression, whereas E2F3 promoted QKI‐6 expression in bladder cancer cells, indicating a negative feedback mechanism in gene regulation." (PMID 31449345, 2019).
breast cancer (61 papers, 2008 to 2026). A primary or metastatic malignant neoplasm involving the breast. "Thus, we injected HCC1954 Her2+ breast cancer cells silenced for E2F3 into mammary fat pads of immunodeficient mice and demonstrated that loss of E2F3 retards tumor growth." (PMID 26512919, 2015). "Notably, among those genetic alteration events whose loss enhances CDK4/6i sensitivity, CDK6, CCND3, CCNE1 and E2F3 were frequently amplified in the genomes of breast cancer patients, whereas among the genes whose loss promotes resistance, RB1, REXO2, PPP2R2A and STT3A were mainly depleted." (PMID 34508104, 2021). "miR-432 was downregulated in breast cancer tissues and functioned as a tumor inhibitor in breast cancer by targeting E2F3 or SLBP." (PMID 37303741, 2023). "Taken together, these results demonstrated that Brachyury knockdown inhibited breast cancer cell proliferation and migration via interaction with E2F3." (PMID 36457717, 2022). "Collectively, the present study indicated that Brachyury is a key regulator in the proliferation and migration of breast cancer cells by targeting E2F3." (PMID 36457717, 2022). "This study provides direct evidence to support the inhibition of breast cancer cell proliferation and migration after knocking down Brachyury, mainly by targeting the E2F3 gene." (PMID 36457717, 2022). "Hsa_circ_0008039/miR-432-5p/E2F3 exhibited oncogenic roles in breast cancer and suppressing hsa_circ_0008039 inhibited proliferation and migration and arrested cell cycle through targeting miR-432-5p, in turn targeting E2F341." (PMID 33514777, 2021). "For instance, miR‐34a expression affects breast cancer invasion in vitro and patient survival via the down-regulation of E2F3 expression." (PMID 33854603, 2021). "Overexpression of E2F1 and E2F3 has been reported to be overexpressed and have a tumor-promoting effect in many cancers including lung cancer, breast cancer, and ovarian cancer." (PMID 34316028, 2021). "Reportedly, E2F3 expression is up-regulated in tumors, such as osteosarcoma and breast cancer, and enhances the proliferation and colony formation of tumor cells." (PMID 34346845, 2021). "An in vitro study showed that siRNA for E2F3 facilitated the silencing of E2F3 overexpression and protected against breast cancer." (PMID 30967995, 2019). "Doxorubicin treatment upregulated miRNAs-449 and DNA-damage responder factors E2F1 and E2F3 in triple negative breast cancer sensitive breast cancer cells, while expression remained unaltered in resistant ones." (PMID 30926829, 2019). "T-VISA-miR-34a induced higher miR-34a level and significantly inhibited breast cancer cell growth in vitro by downregulating E2F3." (PMID 28947999, 2017). "We have previously reported that silencing E2F3 affects mitosis and cytokinesis of Her2+ breast cancer cells." (PMID 29100415, 2017). "In breast cancer, miR-34a was also found to be down-regulated, and restoration of miR-34a showed obvious anti-tumor effects in vitro and in vivo by targeting E2F3." (PMID 28947999, 2017). "T-VISA-miR-34a, which increased miR-34a expression, significantly suppressed breast cancer migration and invasion in vitro by downregulating E2F3." (PMID 28947999, 2017). "We also found that Nek2 acts downstream of the Rb pathway, since Nek2 overexpression rescues back CA/CIN in Her2+ breast cancer cells silenced for Cdk4 or E2F3." (PMID 26512919, 2015). "In this report, we used an orthotopic model of Her2+ breast cancer to address how manipulation of E2F3 levels influences mammary tumorigenesis." (PMID 26512919, 2015). "Taken together, our results indicate that E2F3 silencing decreases mammary tumor growth by reducing percentage of cells undergoing mitosis." (PMID 26512919, 2015). "It was also reported that miR-34a inhibits proliferation, migration, and invasion of breast cancer cells by targeting several genes including E2F3, CD44, and SIRT1, Notch1 and DLL1." (PMID 25826085, 2015).
breast cancer (continued). "E2F's are also overexpressed, exemplified by E2F3 up regulation in various cancers, including breast cancers." (PMID 26512919, 2015). "To investigate the involvement of E2F3 in mammary tumor progression, we used stable silencing of E2F3 in a human Her2+ breast cancer cell line and an orthotopic xenograft mouse model." (PMID 26512919, 2015). "Our group demonstrated that silencing E2F1 or E2F3 suppressed CA/CIN in Her2+ breast cancer, while their overexpression in mammary epithelial cells triggered CA/CIN that respectively correlated with decreases or increases in Nek2 protein levels." (PMID 26512919, 2015). "By combining the bioinformatic and experimental approaches, our results indicated that E2F3 expression was regulated by miR-125b through a target site in the 3′UTR in breast cancer cells." (PMID 22523546, 2012). "First, using univariate Cox-proportional hazards regression models we found that E2F3, MYC and RAS overactivation were associated with poor prognosis in ER+ breast cancer (P < 0.01)." (PMID 21050467, 2010). "Since E2F3 is a proliferation module, this demonstrates once again that in ER- breast cancer, immune response pathways play a much more prominent prognostic role than proliferation." (PMID 21050467, 2010). "We also verified that Th1 (IL12, IFNG) and Th2 (TGFB) modules retained the same prognostic power in multivariate models including E2F3, itself strongly prognostic in ER+ breast cancer but only marginally so in ER negatives." (PMID 21050467, 2010). "Positive controls were expression patterns from mammary tumors from mice carrying transgenic copies of the oncogenes used in the training set or, in the case of Rb null animals, knockouts of an inhibitor of E2F3." (PMID 18937865, 2008). "It has been demonstrated that the level of E2F1 and E2F3 expression were related to the clinical outcomes of multiple tumors, such as lung cancer, pediatric retinoblastoma, breast cancer, hepatocellular carcinoma." (PMID 40070576, 2025). "Meanwhile, inhibiting miR-125b using LNA inhibitor in the miR-125b-high MDA-MB-231 and MDA-MB-415 breast cancer cells resulted in increased E2F3, CDK2, CCNA2 and Bak1 protein expression and increased phosphorylation of Rb, which is indicative of increased G1-S progression with miR-125b inhibition." (PMID 38093346, 2023). "Knockdown of E2F3 also decreased breast cancer cell proliferation and migration." (PMID 36457717, 2022). "Taken together, we reported that Brachyury may act as an oncogenic role in the progression of breast cancer by positively-regulating E2F3 expression." (PMID 36457717, 2022). "Given that both Brachyury and E2F3 could affect breast cancer progression, the relationship between Brachyury and E2F3 in breast cancer remains unclear." (PMID 36457717, 2022). "Apparently, the knockdown of E2F3 decreased breast cancer cell proliferation." (PMID 36457717, 2022). "Likewise, our group previously showed that overexpression of GFP-Nek2 rescues back CA/CIN in Her2 + breast cancer cells that were silenced for E2F3 and also induces invasive protrusions." (PMID 33907253, 2021). "According to previous studies, miR-432-5p could target and regulate E2F3, playing an important role in breast cancer, nasopharyngeal cancer, osteosarcoma, melanoma, and gastric cancer." (PMID 33593338, 2021). "As for breast cancer (BC), Circ_0008039 functions as competing endogenous RNA and increases cell proliferation as well as cells migration via sponging miR-432-5p and altering E2F3." (PMID 31601173, 2019). "Also, silencing E2F1 or E2F3 in Her2+ breast cancer cells suppresses centrosome amplification, while overexpression of E2F1, E2F2, or E2F3a in MCF10A cells is sufficient to trigger centrosome amplification and chromosome instability." (PMID 30381801, 2018).
breast cancer (continued). "Likewise, our laboratory showed that rescuing back centrosome amplification in Her2+ breast cancer cells downregulated for E2F3 by overexpressing GFP-Nek2 induced invasive protrusions in 3D culture." (PMID 30381801, 2018). "Circulating miR-125b expression is reported to correlate with chemoresistace of breast cancer, and importantly, reduction of miR-125b could sensitize breast cancer cell to chemotherapy by targeting E2F3." (PMID 28947999, 2017). "Based on published literature thoroughly described in the introduction, we hypothesized that E2F3 knockdown reduced mammary tumor growth by modifying apoptosis, proliferation or mitosis." (PMID 26512919, 2015). "We found mammary tumor progression was significantly decreased upon E2F3 silencing." (PMID 26512919, 2015). "Down-regulation of miR-125b sensitized breast cancer cells to chemotherapy by targeting E2F3." (PMID 24788655, 2014). "Importantly, E2F3 upregulation was in both cases (retinoblastoma and basal breast cancer) driven by a CNA, since a strong correlation was found between CNA and mRNA expression (FDR P-value cut-off 5.00E-02)." (PMID 25161863, 2014). "Further, this miRNA modulates the mitochondrial functioning and metabolism, represses FGFRL1 and E2F3 expression, which inhibits cell apoptosis in hypoxia response, predicts poor survival in patients with breast cancer and activates notch signalling pathway in angiogenesis." (PMID 23387986, 2013). "E2F3, as a direct target of miR-125b in breast cancer cells, may be involved in miR-125b-mediated chemotherapeutic response." (PMID 22523546, 2012). "However, it is unknown whether and how silencing a single E2F activator, E2F3, affects malignancy of human breast cancer cells." (PMID 26512919, 2015). "In addition, we demonstrated that E2F3 was a direct target of miR-125b in breast cancer cells." (PMID 22523546, 2012). "Moreover, we demonstrated that the E2F3 was a direct target of miR-125b in breast cancer cells." (PMID 22523546, 2012). "This study investigated the time-dependent expression of miR-548c-3p and its post-transcriptional regulation of E2F3 and FOXM1 in MCF-7 breast cancer cells." (PMID 41596697, 2026). "Pathway enrichment revealed associations with cell cycle regulation (E2F3, MKI67), DNA repair (BRCA2), and transcriptional control (MED1), with six priority genes (MED1, BRCA2, E2F3, PITPNB, H1-1, and FARP2) showing established breast cancer relevance." (PMID 41614924, 2026). "TCGA-based analyses confirmed overexpression and hypomethylation of E2F3 and FOXM1 in breast cancer, particularly in triple-negative tumors, and high expression of both genes was associated with poor survival." (PMID 41596697, 2026). "LINC01094 induces cell cycle progression by regulating the microRNA-340-5p (miR-340-5p)/E2F transcription factor 3 (E2F3) molecular axis, as a result, facilitating the spread and progression of breast cancer cells." (PMID 36824662, 2023). "FOXA1, E2F3 and TFDP1 are also identified as miR‐522 targets by pulldown sequencing in breast cancer cells." (PMID 33369228, 2021). "Moreover, mechanistic investigations suggest that hsa_circ_0008039 serves as a ceRNA of miR-432-5p and elevated E2F3 that is identified as a functional target of miR-432-5p, which significantly suppress the proliferation, arrest cell-cycle progression and reduce migration of breast cancer cells." (PMID 33256799, 2020). "Recently, mouse models demonstrated that the E2F activators are required in mammary tumor initiation, since ablation of E2F1 and E2F3 suppressed Her2/Neu and Myc-induced mammary tumorigenesis." (PMID 26512919, 2015). "Although shRNA resulted in an almost complete knockdown of E2F3 protein, differences between the mouse and human tumor systems may be due to the remaining E2F3 protein in cells expressing shE2F3 or differences in transcriptional targets between mouse and human mammary tumors." (PMID 26512919, 2015).
breast cancer (continued). "Using bioinformatics analysis, we found that miR-217 targeted multiple cancer-related genes that have been reported to have a close link with cancers, such as KRAS (pancreatic cancer), E2F3 (hepatocellular carcinoma), and DACH1 (breast cancer)." (PMID 26016795, 2015). "In fact, it has been observed that DNMT1 and E2F3 are candidate targets of miR-152 in HCC, endometrial and breast cancer; BTRC has been shown to ubiquitinate phosphorylated NFKBIA, targeting it for degradation and thus activating NF-κB." (PMID 25330074, 2014). "A large number of genes were predicted as targets of the selected miRNAs, including many well-known genes that are deregulated in breast cancer, such as CCND1, BCL2, E2F3 and PTEN." (PMID 24788655, 2014). "The results showed that five lncRNAs including HOTAIR, DANCR, PVT1, LINC00511, and NEAT1 and 16 miRNAs and five of their targets—VEGFA, BTG2, E2F3, IRAK1, and SMAD4—have significantly different expression patterns in normal individuals compared to those with breast cancer." (PMID 36726376, 2023). "Our group pioneered the study of SGO1 in breast cancer in general by demonstrating, using cBIOPORTAL, that the overexpression of SGO1 in breast tumors correlates with the overexpression of the E2F transcriptional activators E2F1, E2F2, and E2F3." (PMID 37122033, 2023). "In this study, we found that Brachyury knockdown inhibited breast cancer cells proliferation and migration via interacting with E2F3 both in MCF-7 and MDA-MB-231 cell lines, suggesting that Brachyury exerts the biological function by regulating E2F3 genes in breast cancer." (PMID 36457717, 2022). "It is also consistent with our data showing that despite Nek2 rescuing back CA in Her2 + breast cancer cells stably silenced for E2F3, Nek2 did not influence tumor growth." (PMID 33907253, 2021). "Our own studies using an orthotopic model of breast cancer showed that rescuing back centrosome amplification in Her2+ breast cancer cells silenced for E2F3 through the overexpression of GFP-Nek2 did not influence tumor growth or tumor burden." (PMID 30381801, 2018). "Previously, we found that miR-34a could inhibit the proliferation and migration of breast cancer by targeting B-cell lymphoma 2 (Bcl-2), silent information regulator 1 (SIRT1), E2F transcription factor 3 (E2F3) and CD44." (PMID 29037220, 2017). "Using cBioPortal analysis of the TCGA database, we next addressed whether individual genes co-occurred in breast cancers and found significant correlations between E2F1 overexpression and E2F2, E2F1 overexpression and E2F3, and E2F2 overexpression and E2F3." (PMID 29100415, 2017). "E2F1 and E2F3 are oncogenes and have negative correlations with breast cancer patient survival." (PMID 36424626, 2022). "Notably, upregulation of mir-140-5p or suppression of E2F3 or Circ-RNF111 could reduce IC50, cell viability, colony numbers, cell invasion, and glycolysis of paclitaxel-resistant breast cancer lines." (PMID 36132137, 2022). "MiR-26a directly targets several anti-apoptotic proteins, such as E2F Transcription Factor 3 (E2F3), myeloid cell leukaemia-1 (Mcl-1), metadherin (MTDH), enhancer of zeste homolog 2 (EZH2), and phosphatase and tensin homolog (PTEN) which are up-regulated in breast cancer." (PMID 33849540, 2021). "In a recent example, the genetic ablation of the E2F3 transcription factor in macrophages suppresses mammary tumor metastasis into the lungs, but not mammary tumor growth, suggesting that proper macrophage functions and specific microenvironments maintain specific cancer cell functions." (PMID 30381801, 2018). "The goal of this series of experiments is to establish whether silencing E2F3 with or without the introduction of Nek2 modifies tumor progression of HCC1954 breast cancer cells in vivo." (PMID 26512919, 2015). "Thus, it is not surprising that E2F3 be a critical target that mediated the chemotherapeutic resistance in miR-125b overexpressing breast cancer cells." (PMID 22523546, 2012).
breast cancer (continued). "Interestingly, in ER+ breast cancer these pathways were also correlated with MYC and E2F3." (PMID 21050467, 2010). "This, together with our demonstration of a negative correlation between gene expressions of E2F3, CDK2 and CCNA2 with IKBKB expression in breast cancer patients, implicates IKKβ in regulating cell cycle progression in cooperation with miR-125b." (PMID 38093346, 2023). "Previously, we demonstrated that silencing E2F1 or E2F3 suppresses centrosome amplification (CA) and chromosome instability (CIN) in Her2+ breast cancer cells without markedly altering proliferation." (PMID 26512919, 2015). "Upregulation of the activating E2F genes was also found in basal versus not-basal breast cancer: E2F1 (FC = 2.01, P = 8.72E-06), E2F2 (FC = 1.98, P = 2.97E-07), and E2F3 (FC = 1.95, P = 8.13E-17)." (PMID 25161863, 2014). "We further showed that the expression of E2F3, CDK2 and CCNA2 transcripts are negatively correlated with expression of miR-125b but not that of the homologous miR-125a in breast cancer patients, supporting an inhibitory relationship between miR-125b and these cell cycle regulators." (PMID 38093346, 2023). "Similarly to the patterns of expression of mitotic kinases in breast cancers that do not fall under traditional classification (or that failed to classify) FOXM1, E2F1, E2F2, E2F3, and c-Myc are overexpressed in that subtype." (PMID 36494865, 2022).